IL21-AS1 (IL21 antisense RNA 1)
Gene: Long non-coding RNA gene on chromosome 4 (122,618,983 to 122,689,164, forward strand). Ensembl gene ENSG00000227145.
Diseases named in the same sentence as IL21-AS1 in open-access papers:
IL21-AS1 is named in the same sentence as 3 diseases in open-access papers, as found by Europe PMC text mining. Sharing a sentence is not in itself a finding about the gene and the disease. The quoted sentences say what the papers report.
systemic lupus erythematosus (1 paper, 2021). An autoimmune multi-organ disease typically associated with vasculopathy and autoantibody production. "The single nucleotide polymorphism (SNP) rs62324212, located in IL21 antisense RNA 1 (IL21-AS1), has been identified as a genetic risk variant associated with systemic lupus erythematosus (SLE)." (PMID 34895341, 2021).
cancer (1 paper, 2024). A tumor composed of atypical neoplastic, often pleomorphic cells that invade other tissues. "Functional cellular assays demonstrated that IL21-AS1 could protect cancer cells from macrophage-mediated phagocytosis and promote ovarian tumorigenesis via the IL21-AS1–HIF-1α–CD24 and/or IL21-AS1–miR-561-5p–CD24 axes." (PMID 38702326, 2024).
tumours (1 paper, 2024). "The results revealed the colocalization of IL21-AS1 with CD24 and HIF-1α in the cytoplasm, and the signals were specifically increases in hypoxic tumour regions." (PMID 38702326, 2024). "Here, we focus on IL21 antisense RNA 1 (IL21-AS1), a lncRNA that is transcribed from the antisense strand of the IL21 gene locus and has not been reported in tumours, was more highly expressed in OC samples than in normal ovarian tissue." (PMID 38702326, 2024).